RIPK3 (receptor interacting serine/threonine kinase 3)
Diseases named in the same sentence as RIPK3 in open-access papers (continued):
Sharing a sentence is not in itself a finding about the gene and the disease.
Alzheimer disease (12 papers, 2021 to 2025). A progressive, neurodegenerative disease characterized by loss of function and death of nerve cells in several areas of the brain leading to loss of cognitive function such as memory and language. "Necroptosis, a programmed form of necrotic cell death carried out by receptor-interacting serine/threonine protein kinase 1 (RIPK1) and RIPK3, has been found to be implicated in the pathogenesis of Alzheimer’s disease (AD)." (PMID 37458952, 2023). "Ripk1/Ripk3 associated with marked neuroinflammation in animal models of diseases such as multiple sclerosis, amyotrophic lateral sclerosis and Alzheimer’s disease and their inhibition improved the disease phenotype." (PMID 34172992, 2021). "In the brains of Alzheimer’s disease (AD) patients, elevated O-GlcNAcylation of RIPK3 hampers RIPK3 phosphorylation and its interaction with RIPK1." (PMID 40305291, 2025). "The keywords include "necroptosis", "RIPK1", "RIPK3", "MLKL", "pMLKL", "necroptosis inhibitors", "Alzheimer’s disease", and "neurodegeneration"." (PMID 41042431, 2025). "Increased necroptosis has been reported in the postmortem brains of Alzheimer’s disease patients, i.e., an increase in the expression of RIPK1, RIPK3, MLKL, and P-MLKL." (PMID 34515928, 2021). "Hallmarks of necroptosis including the phosphorylation of RIPK1 and elevated levels of insoluble RIPK1, RIPK3 and MLKL are found in post-mortem human pathological samples such as patients with amyotrophic lateral sclerosis (ALS) and Alzheimer’s disease (AD)." (PMID 34689152, 2021). "In the Alzheimer’s disease model, DHA may block necroptosis of THP-1 cells triggered by Aβ via the RIPK1/RIPK3 signaling pathway." (PMID 36895263, 2023). "Necroptosis, which is mediated by receptor-interacting protein kinase 1 (RIPK1 or RIP1), RIPK3 (or RIP3), and the pseudokinase MLKL, promotes necrotic cell death and neuroinflammation in Alzheimer’s disease (AD), amyotrophic lateral sclerosis (ALS), multiple sclerosis (MS), and PD." (PMID 38041169, 2023).
heart failure (12 papers, 2019 to 2026). Inability of the heart to pump blood at an adequate rate to meet tissue metabolic requirements. "In the present study, we aimed to investigate the effect of RIPK3-regulated CaMKII on necroptosis in heart failure (HF) and its underlying mechanism." (PMID 35571197, 2022). "In ischemia and oxidative stress injury, RIPK3 mediates the activation of CaMKII δ, induces myocardial necroptosis and apoptosis, and causes decompensated cardiac remodeling and heart failure." (PMID 35805993, 2022). "Increased RIPK3 expression is also associated with severe cardiac remodeling, cardiac insufficiency, and higher mortality." (PMID 36132224, 2022). "Heart failure patients harboring a genetic variant in the promoter region of RIPK3 gene that increases RIPK3 gene expression tend to exhibit poorer prognosis than those who do not carry such a variant." (PMID 34604361, 2021). "RIPK3 drives the downstream molecule calcium/calmodulin-dependent protein kinase II (CaMKII), causing myocardial necroptosis in cardiac ischemia/reperfusion (I/R) injury and heart failure." (PMID 35805993, 2022). "Necroptosis, a major form of regulated necrosis mediated by RIPK3-centered pathways, is implicated in heart failure; however, it remains unknown whether excessive β-adrenergic stimulation-induced cardiac injury involves necroptosis." (PMID 34604361, 2021). "Studies have shown that upregulation of RIPK3 plays a critical role in ischemic and oxidative stress-induced myocardial cell regulated necrosis, leading to myocardial remodeling and heart failure in addition to apoptosis and inflammation." (PMID 41499472, 2026). "Targeting the RIPK3-CaMKII pathway can protect the rat heart from ischemic and oxidative stress-induced necrotic cell death, myocardial remodeling, and heart failure." (PMID 41499472, 2026). "This suggests that RIPK3 is an important regulatory protein that mediates the pathological mechanisms of heart failure." (PMID 36132224, 2022). "For example, the knockout of RIPK3 endowed the mice with the ability to resist heart failure that was triggered by ischemia/reperfusion, and this was independent of the activation of RIPK1 or MLKL." (PMID 31248365, 2019). "However, depletion of RIPK3 alleviated cardiac insufficiency, CaMKII activation, and necroptosis in TAC-treated mice." (PMID 35571197, 2022). "In conclusion, our results revealed a key mechanism by which necroptosis could be mediated by RIPK3 via the AMPK/Parkin-mitophagy/mPTP opening axis, which provides a potential therapeutic target in the management of heart failure after MI." (PMID 33854696, 2021).
ischemic stroke (12 papers, 2019 to 2025). A stroke disorder caused by obstruction of blood flow to the brain, due to thrombotic (local blood clot formation) or embolic (due to a blood clot or other material traveling from another site) event. "Importantly, the simultaneous knockdown of Ripk1 and Nsf exerted neuroprotective effects on ischemic stroke by modulating the RIPK1/RIPK3/MLKL signaling pathway associated with necroptosis in neurons." (PMID 38919602, 2024). "The simultaneous knockdown of Ripk1 and Nsf exerts its effects on ischemic stroke through the RIPK1/RIPK3/ mixed lineage kinase domain-like protein (MLKL) signaling pathway involved in necroptosis." (PMID 38919602, 2024). "Enhanced HIF-1α levels after ischemic stroke appear to be involved in RIPK3/MLKL activation, leading to activation of the NLRP3 inflammasome." (PMID 38674050, 2024). "Recent findings support the fact that the inhibition of RIPK3/AMPK-mediated mitophagy is beneficial for reducing neuronal apoptosis in mice following an ischemic stroke." (PMID 38786094, 2024). "In previous studies, necroptosis was found to contribute to ischemic stroke by intervening in the RIPK1/RIPK3/MLKL signaling pathway in neurons and microglia." (PMID 38026442, 2023). "Recently, it was shown for the first time that p-RIPK1- (Ser166) and RIPK3/MLKL-dependent necroptosis pathways are activated in the modeling of ischemic stroke." (PMID 35054920, 2022). "Given that at its core, tissue ischemia, infarction, and cell death underlie ischemic stroke, the role of necroptosis, RIPK1, and RIPK3 in stroke has become a topic of interest." (PMID 33142926, 2020). "The results showed that ischemic stroke induced the increase of RIPK3, MLKL and p-MLKL (Ser 345) expression levels in the ipsilateral striatum at 24 h after MCAO." (PMID 31440386, 2019). "Nec-1 treatment was able to protect against ischemic neuronal death by inhibiting RIPK1-mediated RIPK3/MLKL-dependent necroptosis in rat brains following ischemic stroke." (PMID 31440386, 2019). "In the middle cerebral artery occlusion (MCAO) model in vivo and the oxygen–glucose deprivation/re-oxygenation (OGD/R) cellular model in vitro, blocking the RIPK1/RIPK3/MLKL pathway could effectively alleviate ischemic stroke injuries." (PMID 38026442, 2023). "In ischemia–reperfusion injury, the upregulation of RIPK1 and RIPK3 results in CypD-mediated mPTP opening, Ca2+ influx and ROS generation, and the inhibition of CypD-mediated mPTP opening could alleviate ischemic stroke-induced necroptosis." (PMID 38026442, 2023). "Several studies have indicated that ROS generation leads to PARP activation, AIF release, RIPK1 autophosphorylation, RIPK3 recruitment and NLRP3 inflammasome activation in response to ischemic stroke." (PMID 38026442, 2023). "By intervening in the RIPK1/RIPK3/MLKL pathway, previous studies have demonstrated that necroptosis contributes to ischemic stroke." (PMID 38026442, 2023). "Several studies have demonstrated that RIPK1, RIPK3 and MLKL participate in the pathogenesis of ischemic stroke after the activation of DRs." (PMID 38026442, 2023). "Intracerebral hemorrhage, which can be seen in humans when ischemic strokes undergo hemorrhagic conversion, was significantly reduced in RIPK1 kinase dead mice and Ripk3−/− mice." (PMID 33142926, 2020). "HIF-1α also regulates necroptosis-related proteins, such as RIPK3 and MLKL, in ischemic stroke." (PMID 38674050, 2024). "RIPK3−/− did not reduce neuronal death in an ischemic stroke model, but RIPK3−/− mice had reduced biochemical markers of apoptosis in a CCI model, whereas MLKL−/− mice had markedly reduced acute neuronal death after ICH." (PMID 34753914, 2021). "Knockout of receptor-interacting serine/threonine protein kinase 3 (RIPK3) or mixed-lineage kinase domain-like protein (MLKL), the key regulators of the necroptotic pathway, can reduce the severity of renal ischemia‒reperfusion (I/R) injury and ischemic stroke." (PMID 36828808, 2023).
dermatitis (11 papers, 2014 to 2024). An inflammatory process affecting the skin. "Here we show that ZBP1 causes skin inflammation by inducing RIPK3-mediated necroptosis and RIPK1-caspase-8-mediated apoptosis in keratinocytes." (PMID 38849574, 2024). "Ablation of RIPK3 in these KC-selective RIPK1-deficient mice averts skin inflammation, indicating the high potency of necroptosis in driving dermatitis." (PMID 38649745, 2024). "Our genetic studies showed that epidermis-specific ablation of FADD or caspase-8 caused skin inflammation by inducing RIPK3-MLKL-dependent necroptosis of keratinocytes." (PMID 38849574, 2024). "Collectively, these results showed that ZBP1ca expression caused skin inflammation by inducing RIPK3-MLKL-dependent necroptosis and to a lesser extent caspase-8-dependent apoptosis in keratinocytes." (PMID 38849574, 2024). "Amelioration of dermatitis via loss of RIPK3 indicated a significant role for RIPK3-mediated necroptosis in driving T cell-induced innate inflammation." (PMID 31462647, 2019). "This complicates interpretation of the role of RIPK3 in a disease, particularly when IL-1 is pathogenic such as in cpdm dermatitis." (PMID 25443632, 2014). "Strikingly, combined Ripk3 deficiency and Casp8 heterozygosity completely prevented the cpdm dermatitis in all but one of the mice analyzed at 42 to 45 weeks of age, prevented liver inflammation and grossly restored splenic architecture." (PMID 25443632, 2014). "Moreover, transgenic expression of C-terminally truncated constitutively active ZBP1 (ZBP1ca) in mouse epidermis caused skin inflammation that was only partially inhibited by abrogation of RIPK3-MLKL-dependent necroptosis and fully prevented by combined deficiency in MLKL and caspase-8." (PMID 38849574, 2024). "Consistent with previously published reports, Shpnm/m mice manifested onset of dermatitis at around 11 weeks of age while Shpnm/m; Ripk3−/− animals presented a modest delay in the appearance of the dermatitis." (PMID 38783091, 2024). "These mice are known to succumb to aberrant skin inflammation induced by RIPK3 and MLKL-mediated necroptosis." (PMID 38783091, 2024). "Specifically, TNF-induced apoptosis is responsible for skin inflammation since Casp8 heterozygosity can significantly ameliorate the dermatitis, while multi-organ inflammation is predominantly driven by RIPK3/MLKL-induced necroptosis." (PMID 38783091, 2024). "In accordance with previous studies histological analysis showed a very mild amelioration of the epidermal thickness in Shpnm/m; Ripk3−/− which was confirmed by the dermatitis score." (PMID 38783091, 2024). "Mice with specific deletion of Fadd or Caspase‐8 in epidermal keratinocytes also develop severe skin inflammation that is abrogated by concomitant Ripk3 deletion, implying that increased necroptosis triggers skin inflammation." (PMID 26085216, 2015). "However, since the role of FADD can only be addressed in a RIPK3-deficient background, it remains possible that FADD-dependent apoptosis and RIPK3-dependent necroptosis might share a redundant function in inducing the cell death of Sharpin-deficient keratinocytes and triggering skin inflammation." (PMID 25443631, 2014). "We therefore hypothesized, that ZBP1ca induces keratinocyte death and skin inflammation by interacting with RIPK3 via its RHIM." (PMID 38849574, 2024). "Mice with epidermal keratinocyte-specific ablation of RIPK1 (RIPK1E-KO) develop severe skin inflammation mediated by RIPK3-MLKL-dependent keratinocyte necroptosis, which is strongly suppressed by ZBP1 deficiency but only partially ameliorated by TNFR1 knockout." (PMID 38849574, 2024). "Indeed, while concomitant deletion of RIPK3 and Caspase-8 completely prevents the inflammatory lesions, loss of TNFR1 delays the onset of dermatitis, but mutant mice still succumb later in life due to severe skin inflammation." (PMID 35740456, 2022).
dermatitis (continued). "Consistent with the apoptotic cell death observed in vitro, genetic ablation of Ripk3 in Hoil-1E-KO or the loss of Mlkl in HoipE-KO mice failed to prevent aberrant cell death and skin inflammation and did not delay the postnatal lethality." (PMID 30254289, 2018). "Ripk3 deletion provided only a modest and variable delay in the presentation of dermatitis." (PMID 25443632, 2014). "Double deficient Sharpincpdm/cpdm;Ripk3−/− mice developed skin lesions similar to those of Sharpincpdm/cpdm mice, demonstrating that RIPK3 deficiency did not prevent the development of skin inflammation." (PMID 25443631, 2014). "To address whether MLKL-dependent necroptosis drives skin inflammation also in Casp8E-KO mice, we crossed them to MlklAA/AA mice, which express a mutated version of MLKL that cannot be phosphorylated by RIPK3 due to substitution of serines at positions 345 and 347 to alanines." (PMID 38849574, 2024). "In contrast to RIPK3 deficiency, deletion of Mlkl did not even delay appearance of the dermatitis." (PMID 25443632, 2014). "Here we identified a critical interplay between RIPK3-MLKL-dependent necroptosis and FADD-caspase-8-mediated apoptosis that controls skin inflammation downstream of TNFR1 and ZBP1." (PMID 38849574, 2024). "This is suggesting that RIPK3-mediated inflammation contributes to dermatitis independently of MLKL activation and that apoptotic cell death is the main driver of dermatitis." (PMID 38783091, 2024). "Caspase-8 heterozygosity significantly delays dermatitis onset, while co-deletion of FADD (in the skin) and RIPK3 was required to entirely ablate skin inflammation, implying that inflammation is primarily driven by apoptosis, with a minor role for necroptosis." (PMID 33924766, 2021). "However, apoptosis may also contribute to some extent because loss of RIPK3 failed to fully cure dermatitis in Sharpinfl/flFoxp3Cre mice." (PMID 31462647, 2019). "Our findings that inhibition of RHIM-dependent RIPK3 signaling did not fully prevent skin inflammation in ZBP1caE-het mice suggested that ZBP1ca could induce keratinocyte cell death by activating RIPK1." (PMID 38849574, 2024). "Interestingly, while co-deletion of Sharpin and RIPK3 delays the onset of the dermatitis, MLKL co-deletion does not affect the skin inflammation observed in the Shpnm/m." (PMID 38783091, 2024). "Since deficiency of caspase-8 or FADD alone in epidermal keratinocytes triggers a RIPK3-dependent skin inflammation, we could not directly investigate the role of FADD or caspase-8 in the TNF-induced death of Sharpin-deficient keratinocytes in vivo." (PMID 25443631, 2014). "Therefore, mutation of the RIPK3 RHIM strongly ameliorated but could not fully prevent keratinocyte death and skin inflammation in ZBP1caE-hetRipk3mR/mR mice, showing that ZBP1ca drives cell death and inflammation by both RIPK3-dependent and RIPK3-independent mechanisms." (PMID 38849574, 2024). "Collectively, these results demonstrate that caspase-8-mediated apoptosis is responsible for the lethal dermatitis in mice lacking HOIP or HOIL-1 in keratinocytes and that RIPK3/MLKL-mediated necroptosis does not contribute to the disease." (PMID 30254289, 2018). "Address the role necroptosis in the pathogenesis of cpdm mice, ablation of RIPK3 slightly delayed the appearance of the skin lesion in cpdm mice, whereas ablation of MLKL did not influence dermatitis in these mice." (PMID 26085216, 2015). "As keratinocyte apoptosis and skin inflammation in Sharpincpdm/cpdm mice were suppressed by epidermal-specific deletion of FADD or TRADD, we sought to investigate how the lack of FADD, TRADD, and RIPK3 proteins impact on TNF-induced cell viability in Sharpin-deficient cells." (PMID 25443631, 2014).
diabetic cardiomyopathy (11 papers, 2021 to 2025). Diabetic cardiomyopathy is a disorder of the heart muscle in people with diabetes. "Deficiency of RIPK3 mitigated myocardial injury, improved cardiac function, suppressed CaMK II activation, and reduced necroptosis in mice with diabetic cardiomyopathy mice." (PMID 34977874, 2021). "Current studies suggest that RIPK3-dependent necrosis is associated with the occurrence of several cardiovascular diseases, such as myocardial ischemia-reperfusion injury, atherosclerosis, and diabetic cardiomyopathy." (PMID 36046685, 2022). "RIPK3 deficiency alleviated myocardial injury, improved cardiac function, and attenuated necroptosis in mice with STZ-induced diabetic cardiomyopathy." (PMID 35370692, 2022). "Recent studies have reported that in the myocardial tissue of high-glucose-driven diabetic cardiomyopathy mice undergoing CaMKII δ alternative splicing disorder, inhibiting RIPK3 can alleviate CaMKII δ dysfunction in cardiomyocytes." (PMID 36046685, 2022). "In summary, Nec-1-dependent inhibition of RIPK1/RIPK3 is a viable treatment strategy for diabetic cardiomyopathy." (PMID 35165268, 2022). "Taken together, CaMKII activation and necroptosis augment in diabetic cardiomyopathy via a RIPK3-dependent manner." (PMID 34194608, 2021). "Silencing RIPK1/RIPK3 significantly reduces autophagy-associated proteins such as LC3-II and p62, indicating that the RIPK1/RIPK3 pathway is crucial for regulating autophagic flux in diabetic cardiomyopathy." (PMID 40004130, 2025). "The research suggests that RIPK3 may be an important target of diabetic myocardial damage, which provides a new idea for prevention and treatment of diabetic cardiomyopathy." (PMID 35805993, 2022). "However, the role of the RIPK1/RIPK3 signaling pathway in myocardial fibrosis and related diabetic cardiomyopathy is still unclear." (PMID 35165268, 2022). "Moreover, CaMK II activation and necroptosis augment in diabetic cardiomyopathy were achieved via a RIPK3‐dependent manner." (PMID 34977874, 2021). "Importantly, activated RIPK3 can be transported to the mitochondrial membrane continuously triggering mPTP opening through multiple pathways, thus establishing a positive feedback loop and hastening necroptosis in diabetic cardiomyopathy and I/R heart." (PMID 40635895, 2025). "In diabetic cardiomyopathy, high glucose–induced mitochondrial ROS activates the circOGDH/HMGB1/RIPK3 axis in cardiomyocytes, leading to the activation of caspase-3, GSDMD, and p-MLKL, ultimately leading to heart failure." (PMID 41583472, 2025). "To determine the role of RIPK3 in MLKL phosphorylation and diabetic cardiomyopathy, we induced type-1 diabetes in RIPK3 knockout and wild-type mice by STZ injection." (PMID 36030201, 2022). "To examine if targeting RIPK3 is a therapeutic approach to reduce diabetic cardiomyopathy, we gave GSK’872, a pharmacological inhibitor of RIPK3, to STZ-injected mice right after induction of hyperglycemia for a total of 2 months." (PMID 36030201, 2022). "Deletion of RIPK3 was reported to attenuate myocardial injury and heart dysfunction in streptozocin (STZ)-induced diabetic mice, suggesting a potential role of necroptosis in diabetic cardiomyopathy." (PMID 36030201, 2022).